BDNF (brain derived neurotrophic factor)
Diseases named in the same sentence as BDNF in open-access papers (continued):
Sharing a sentence is not in itself a finding about the gene and the disease.
pheochromocytoma (4 papers, 2010 to 2022). "Studies show that H2S protects PC12 cells (neurocytes derived from pheochromocytoma of adrenal medulla of rat) and hippocampal slices against oxidative damage and toxicity by regulating BDNF-TrkB pathway, suggesting a close association of H2S and BDNF-TrkB pathway in CNS." (PMID 30577733, 2018). "Thus, the effects of p-cresol on the secretion of brain-derived neurotrophic factor (BDNF) and neurofilament subunit expression were examined using rat pheochromocytoma cells (PC-12 cells)." (PMID 35434277, 2022). "Accordingly, we investigated the effects of p-cresol on the secretion of brain-derived neurotrophic factor (BDNF) and neurofilament (NF) subunit expression in model experiments using rat pheochromocytoma cells (PC-12 cells)." (PMID 35434277, 2022). "PC12 is a cell line derived from a pheochromocytoma of the rat adrenal gland and secretes neurotrophins such as nerve growth factor (NGF) and brain-derived neurotrophic factor (BDNF)." (PMID 20625543, 2010).
premenstrual syndrome (4 papers, 2022 to 2025). "High flavonoid intake induced serum BDNF levels, improved cognitive function in healthy subjects, and, in women with premenstrual syndrome in randomized, double-blind, placebo-control trials, curcumin increased serum BDNF levels." (PMID 40243512, 2025).
prostate tumor (4 papers, 2021 to 2023). "CAFs isolated from prostate tumor stroma of AA patients secrete higher levels of pro-inflammatory cytokines and growth factors such as brain-derived neurotrophic factor (BDNF), VEGF, and fibroblast growth factor 7 (FGF7) compared to their EA counterparts." (PMID 34071280, 2021). "However, in the context of cancer, it may be undesirable to target BDNF and TrkB directly by systemic treatment, as both are expressed in prostate tumors and their dysregulation can contribute to tumor progression." (PMID 37788996, 2023). "Relevant experiments have shown that BDNF is highly expressed in prostate stromal cells and the androgen-responsive LNCaP prostate tumor cell line; on the contrary, it is not expressed in the androgen refractory TSU-pr1 prostate tumor cell line." (PMID 36661494, 2022).
pulmonary hypertension (4 papers, 2010 to 2024). Increased pressure within the pulmonary circulation due to lung or heart disorder. "In arteries of patients with pulmonary hypertension, BDNF expression and release was higher at baseline." (PMID 26192455, 2015). "The present study documents the yet unreported finding of reduced serum BDNF levels in SSc, particularly in the diffuse SSc subset, as well as in patients with severe forms or pulmonary hypertension." (PMID 21085492, 2010). "In contrast, BDNF levels were lower in SSc patients than in controls (1121.9±158.1 vs 1372.9±190.9 pg/mL, p<0.0001), especially in pulmonary arterial hypertension and diffuse SSc as compared to limited forms (all p<0.05)." (PMID 21085492, 2010). "Moreover, in mice, BDNF/TrkB signaling also enhanced the proliferation of smooth muscle cells in mice with pulmonary hypertension." (PMID 38791682, 2024). "Low BDNF serum levels were not previously documented in SSc, particularly in the diffuse SSc subset and in patients with pulmonary hypertension or anti-Scl-70 antibodies." (PMID 21085492, 2010).
Senile plaques (4 papers, 2013 to 2024). Senile plaques are extracellular deposits of amyloid in the gray matter of the brain. "Alterations in BDNF levels are observed in the cortex and hippocampus of AD patients, and BDNF immunoreactivity is associated with senile plaques." (PMID 23700479, 2013). "Changes in BDNF expression were observed in AD patients and BDNF immunoreactivity was closely associated with senile plaques." (PMID 23700479, 2013). "Infact, a significant increase of BDNF and the receptor TrkB has been shown in hippocampus,parietal cortex, astrocytes and senile plaques." (PMID 28068360, 2017).
trigeminal neuralgia (4 papers, 2020 to 2024). Trigeminal neuralgia is a nerve disorder that causes a stabbing or electric-shock-like pain in parts of the face. "Previous work in our laboratory has shown that palmatine treatment can inhibit trigeminal neuralgia, which may be related to the down-regulation of the expression of BDNF and CGRP in trigeminal ganglion neurons." (PMID 34366788, 2021). "Inhibition of the communication between neurons and glial cells can down-regulate the expressions of BDNF and CGRP in trigeminal ganglion neurons, and ultimately inhibit the pain transmission of trigeminal neuralgia." (PMID 34366788, 2021).
vitamin A deficiency (4 papers, 2014 to 2022). Deficiency of vitamin A due to malnutrition, malabsorption, or dietary lack. "Of the potential downstream elements that RA may control in the hippocampus, the circadian rhythm of brain-derived neurotrophic factor (BDNF) is disrupted in response to vitamin A deficiency." (PMID 24266881, 2014). "Vitamin A deficiency decreases maintenance levels of nerve growth factor (NGF) and brain-derived neurotrophic factor (BDNF), which ordinarily protect the retina from oxidative stress injury and stimulate repair." (PMID 32582807, 2020). "Vitamin A deficiency reduced the level of RXRβ mRNA, changed the rhythm amplitude of the PER1, REV-ERB genes and REV-ERB protein, and phase-shifted the daily peaks of RORα protein as well as BMAL1, RORα, RC3 and BDNF mRNA levels." (PMID 36466383, 2022).
vitamin D deficiency (4 papers, 2019 to 2025). A nutritional condition produced by a deficiency of VITAMIN D in the diet, insufficient production of vitamin D in the skin, inadequate absorption of vitamin D from the diet, or abnormal conversion of vitamin D to its bioactive metabolites. "Other biomarkers that were found to be associated with POD include BDNF, reduced cholinesterase activity, serum leptin, hypoalbuminaemia and vitamin D deficiency." (PMID 30797230, 2019). "The exploration of the mechanism in this study only focused on inflammatory indicators, without involving neurotransmitters (such as serotonin, BDNF) and VDR gene polymorphisms, and the sample only covered people with vitamin D deficiency." (PMID 40821024, 2025).
adenoma (3 papers, 2013 to 2026). A neoplasm arising from the epithelium. "ROC analysis revealed that when CRC is compared with adenomas, the serum levels of BDNF provided a diagnostic efficacy with an AUC of 0.719, indicating that serum BDNF may likely have a potential role in the early diagnosis of CRC." (PMID 33628340, 2021). "Here we describe a retrospective study utilizing an ELISA-based immunoassay to measure the protein concentration of serum BDNF in adenomas and patients with CRC and to investigate its potential usefulness as a blood-based biomarker for the diagnosis of CRC." (PMID 33628340, 2021). "BDNF expression was significantly higher in gallbladder adenocarcinoma than in peritumoral tissues, adenoma, polyps and chronic cholecystitis samples." (PMID 23531103, 2013). "When all100 gallbladder adenocarcinoma, 46 peritumoral, 30 adenoma, 15 polyp and 35 chronic cholecystitis samples were assessed, the positive rate of BDNF was inversely related to that of BMPR1A, due to the analysis of Pearson correlation coefficients (r = −7.482, P < 0.05)." (PMID 23531103, 2013). "BDNF was significantly higher (positive) and BMPR1A was significantly lower (negative) in gallbladder adenocarcinoma than in peritumoral tissues, adenoma, polyps, and chronic cholecystitis (P < 0.01 for both)." (PMID 23531103, 2013). "The BDNF and BMPR1A expression of gallbladder adenocarcinoma, peritumoral tissues, adenoma, polyp and chronic cholecystitis were Immunohistochemically determined." (PMID 23531103, 2013). "Analysis of the serum levels of BDNF revealed that the serum level of BDNF in patients with CRC (10.64 ± 3.84 ng/mL) was significantly higher than the level in HC (4.69 ± 1.69 ng/mL; p < 0.0001) and patients with adenomas (5.97 ± 2.09 ng/mL; p < 0.001)." (PMID 33628340, 2021). "Baseline BDNF levels correlated inversely with OCT and visual field measures, particularly in non-functioning adenomas (R = -0.70 to -0.80, p < 0.01)." (PMID 41898472, 2026).
Airway obstruction (3 papers, 2006 to 2024). Obstruction of conducting airways of the lung. "In this respect, it is interesting to note that while both NGF and BDNF have been shown to evoke airway hyperreactivity in animal studies, they may have distinct roles in allergen-dependent airway obstruction." (PMID 16441896, 2006). "Significantly negative correlations between BDNF count and the situation of airway obstruction were found in non-allergic NPs." (PMID 38827877, 2024).
alexithymia (3 papers, 2018 to 2024). An agnosia that is a deficiency in understanding, processing, or describing emotions. "On the other hand, for the BDNF gene, the candidate variant was Val66Met, specifically the 66Met allele, in patients with alexithymia." (PMID 39202385, 2024). "The main candidate genes associated with alexithymia are from the serotoninergic pathway (SLC6A4, HTR1A and HTR2A) and neurotransmitter metabolism (DRD2/ANKK1, COMT, BDNF, and OXTR)." (PMID 39202385, 2024).
Arterial thrombosis (3 papers, 2018 to 2025). The formation of a blood clot inside an artery. "In particular, BDNF Val66Met polymorphism is associated to propensity for arterial thrombosis in a cohort of patients with acute myocardial infarction." (PMID 30347685, 2018). "In novelty-suppressed feeding and FeCl3-induced arterial thrombosis models, BDNF Met/Met mice display significant behavioural deficits, reduced hippocampal BDNF levels, and rapid carotid artery thrombosis, accompanied by elevated NE levels in the bone marrow and plasma." (PMID 41301929, 2025).
autoimmune encephalitis (3 papers, 2013 to 2025). Inflammation of the brain secondary to an immune response triggered by the body itself. "Human BMMSCs can improve neurological functional recovery in mice with experimental autoimmune encephalitis, possibly via a reduction of inflammatory infiltrates and areas of demyelination, stimulation of oligodendrogenesis, and by elevating brain-derived neurotrophic factor (BDNF) expression." (PMID 23554816, 2013).
cerebral artery occlusion (3 papers, 2018 to 2023). "In fact, heterozygous BDNF-deficient (BDNF+/−) or homozygous NT4-deficient (NT4−/−) mice display increased susceptibility to transient middle cerebral artery occlusion (tMCAO)-induced ischemic injury." (PMID 34572573, 2021). "NSC-CM include neurotrophic factors, like GDNF and BDNF, while BDNF or GDNF was confirmed to exert antiapoptotic effect after transient middle cerebral artery occlusions in rats." (PMID 29765412, 2018).
cerebral malaria (3 papers, 2019 to 2022). A sequestration of Plasmodium falciparum in the brain, which can cause coma and/or seizures. "In mice that survived experimental cerebral malaria, a single dose of MSCs conferred a protective effect on the blood-brain barrier, reduced the number of adherent leukocytes, and restored BDNF protein levels within 24 h of administration." (PMID 32843073, 2020). "Future studies will determine the mechanisms mediating dysregulation of BDNF signaling in cerebral malaria pathogenesis." (PMID 31844087, 2019). "In parasitic diseases, the role of neurotrophins is poorly known, but changes in BDNF availability could be involved in the pathogenesis of cerebral malaria." (PMID 35563321, 2022). "The downregulation of BDNF may be a point of no return for the neurological damages observed in cerebral malaria." (PMID 32843073, 2020).
Cluster headache (3 papers, 2012 to 2024). A type of headache characterized by repeated attacks of unilateral pain lasting 15 to 180 minutes and associated with local autonomic signs. "Cluster headache patients showed significantly higher BDNF concentrations inside (n = 42) and outside cluster bouts (n = 24) compared with healthy controls (P < 0.01, P < 0.05)." (PMID 22584531, 2012). "BDNF is increased during migraine attacks, and in cluster headache, further supporting the involvement of BDNF in the pathophysiology of these primary headaches." (PMID 22584531, 2012). "Elevation of BDNF during and outside cluster bouts might result from continuous trigeminal activation in cluster headache patients, which should be investigated in future trials." (PMID 22584531, 2012). "The present study is the first to report an increase of BDNF in patients with cluster headache." (PMID 22584531, 2012).
deficiencies (3 papers, 2019 to 2021). "Interestingly, the loss of BDNF in mice is associated with brain monoamine deficiencies and an increased appearance of stress-induced depressive-like behavior." (PMID 31251738, 2019).
dental caries (3 papers, 2023 to 2025). The decay of a tooth, in which it becomes softened, discolored, and/or porous. "In summary, our studies provide findings on the roles of BDNF-TrkB in inflammation-induced tertiary dentin formation and its underlying mechanism that will help to identify novel therapeutic pathways of treating dental caries." (PMID 37508514, 2023). "In this study, we further explore the role of various inflammatory agents in modulating BDNF receptor, TrkB, as well as the potential therapeutic applications of BDNF overexpression in DPSCs using CRISPR technology for treating dental caries." (PMID 39713307, 2025). "The overexpression of BDNF in DPSCs has been shown to enhance their regenerative capabilities, which may be particularly beneficial in the context of dental caries where inflammation and tissue damage are prominent." (PMID 39713307, 2025).
dilated cardiomyopathy (3 papers, 2020 to 2022). Cardiomyopathy which is characterized by dilation and contractile dysfunction of the left and right ventricles. "All facts clearly showed that dilated cardiomyopathy associated with cardiomyocyte hypertrophy was one of the pathological phenotypes caused by deletion of cardiomyocyte-derived BDNF in young adult hearts." (PMID 36061561, 2022). "Along the differentiation trajectory, early DEG were associated with ECM-receptor interaction and TGFβ signaling as well as focal adhesion, while late in this trajectory expressed genes were associated with dilated cardiomyopathy, syndecan 4 pathway, translation and the BDNF signaling pathway." (PMID 35641541, 2022). "Using a knock-in mouse model (Val66Met mice), which harbors the BDNF G→A substitution, we discovered a role for the Val66Met polymorphism in modulating cardiomyocyte contractility as a possible mechanism contributing to altered heart function in the context of dilated cardiomyopathy." (PMID 33050457, 2020). "Brain-derived neurotrophic factor (BDNF) is a neuronal growth and survival factor that harbors cardioprotective qualities that may attenuate dilated cardiomyopathy." (PMID 33050457, 2020). "One explanation might be that this was a parallel change to adapt to the changes associated with dilated cardiomyopathy and other pathological phenotypes seen in MYH6-Cre-BDNF–/– hearts, which require more gene activation to compensate for the ablation of BDNF in cardiomyocytes." (PMID 36061561, 2022).
drug dependence (3 papers, 2017 to 2024). "However, a role for BDNF in the motivated behavior and the mesolimbic dopamine system in drug dependence still remains unclear." (PMID 30416533, 2018). "Thus, it can be expected that acupuncture can reduce drug relapse by improving negative emotional state in drug dependence through modulation of the BDNF-mediated mesolimbic dopamine pathway." (PMID 30416533, 2018).
dry eye (3 papers, 2019 to 2023). "Polymorphisms in the brain-derived neurotrophic factor gene were associated with dry eye in a study of 64 dry eye patients with 51 controls." (PMID 36430547, 2022). "Additionally, our results indicate that BDNF is a key factor in dry eye pathogenesis, which we hope will be useful for future research on the relationship between BDNF and dry eye." (PMID 30833600, 2019). "The cognitive function, working memory, dry eye, AChE, MAO, MAO-A, MAO-B, and GABA-T activities, BDNF, HAC, HDAC, and DNMT activities, pH, and amount of lactic acid-producing bacteria, particularly Lactobacillus and Bifidobacterium spp." (PMID 37630690, 2023).
Duchenne muscular dystrophy (3 papers, 2020 to 2024). Duchenne muscular dystrophy (DMD) is a neuromuscular disease characterized by rapidly progressive muscle weakness and wasting due to degeneration of skeletal, smooth and cardiac muscle. "In patients with Duchenne muscular dystrophy, the rs6265 polymorphism is associated with altered relationship between plasma BDNF levels and LVEF and worse skeletal muscle performance." (PMID 33050457, 2020). "We previously demonstrated an association of circulating BDNF with better heart function in a small cohort of Duchenne muscular dystrophy (DMD) patients." (PMID 33050457, 2020). "We previously showed that BDNF correlates with better cardiac function in Duchenne muscular dystrophy (DMD) patients." (PMID 33050457, 2020).
Dysmenorrhea (3 papers, 2022 to 2024). Pain during menstruation that interferes with daily activities. "Additionally, correlation coefficients for the association analysis between the mRNA expression of BDNF or TrKB in eutopic endometrium and the dysmenorrhoea VAS score were r = 0.52 and r = 0.56 for BDNF and TrKB, respectively (P < 0.05)." (PMID 35300713, 2022). "We also found that there was a moderate positive correlation between BDNF or TrKB expression in the eutopic endometrium and the dysmenorrhoea VAS score." (PMID 35300713, 2022).
dysthymia (3 papers, 2020 to 2025). "Many researchers suggest that SUMOylation disorders contribute to the destabilization of neuroplasticity pathways (including Brain-derived Neurotrophic Factor (BDNF-TrkB)) and reduce the adaptive capacity of the nervous system in PTSD and dysthymia." (PMID 41155506, 2025).
emotional instability (3 papers, 2023 to 2025). "However, disruptions in the balance of BDNF, MLT, and NE—such as reduced BDNF and elevated MLT and NE—may contribute to SZ-related changes, including impaired synaptic plasticity, dysregulated sleep-wake cycles, and emotional instability." (PMID 40375951, 2025).
eosinophilia (3 papers, 2020 to 2024). "We have shown that the increased expression of BDNF in non-allergic NPs was associated with tissue eosinophilia." (PMID 38827877, 2024).
epilepsy syndrome (3 papers, 2014 to 2025). A syndrome that has a characteristic cluster of clinical features and/or lectroencephalographic (EEG) findings that reflect underlying epileptic activity. "Our analysis reveals that JAK/STAT signaling regulates many of the genes associated with epilepsy syndromes where BDNF levels are markedly elevated." (PMID 31455240, 2019). "However, it is believed that structural rearrangements responsible for maintenance of epileptic syndrome might be triggered by trophic factors such as BDNF (brain derived neurotrophic factor) that is involved in various signaling mechanisms that may be influenced by seizure activity." (PMID 24605339, 2014).
focal segmental glomerulosclerosis (3 papers, 2017 to 2022). A renal disorder characterized by sclerotic lesions in the glomeruli. "Recently, administration of BDNF was shown to increase the number and length of cultured podocyte processes, and also improved glomerular damage by repairing podocyte injury in a mouse model of focal segmental glomerulosclerosis." (PMID 28575038, 2017).